LGI3 (leucine rich repeat LGI family member 3)
Description:
May participate in the regulation of neuronal exocytosis.
Synonyms: LGIL4; IDDMDS
Tractability: Antibody: UniProt places it where antibodies can reach, with high confidence; its Gene Ontology location is reachable by antibodies, with high confidence; UniProt predicts a signal peptide or a membrane-spanning region.
Gene: Protein-coding gene on chromosome 8 (22,146,824 to 22,157,084, reverse strand). Ensembl gene ENSG00000168481.
Subcellular location: Secreted; Cytoplasmic vesicle, secretory vesicle, synaptic vesicle; Synapse, synaptosome; Cell projection, axon
Pathways (Reactome):
Developmental Biology: LGI-ADAM interactions
Gene Ontology:
Biological process: regulation of exocytosis
Cellular component: extracellular region; juxtaparanode region of axon; non-collagenous component of interstitial matrix; synaptic vesicle; axon; synapse
Genetic constraint (gnomAD): Loss-of-function variants: 47 observed, 56.19 expected, observed/expected ratio (o/e) 0.84, 90% interval 0.66 to 1.07. The upper end of that interval is the gene's LOEUF score, 1.07, which puts it in group 4 of 6, group 1 being the genes least tolerant of losing a copy. Missense variants: 636 observed, 721.18 expected, observed/expected ratio (o/e) 0.88, 90% interval 0.83 to 0.94. Synonymous variants: 313 observed, 310.13 expected, observed/expected ratio (o/e) 1.01, 90% interval 0.92 to 1.11.
Homologues: Orthologues: chimpanzee LGI3 (99% identical), macaque LGI3 (99% identical), pig LGI3 (98% identical), guinea pig LGI3 (97% identical), dog LGI3 (97% identical), mouse Lgi3 (97% identical), rabbit LGI3 (96% identical), rat Lgi3 (96% identical), zebrafish lgi3 (58% identical), Drosophila melanogaster kek3 (17% identical), Drosophila melanogaster Con (14% identical), Caenorhabditis elegans sma-10 (14% identical), and 1 more. Paralogues in human: LGI1 (51% identical), LGI2 (51% identical), LGI4 (41% identical), LRIG1 (19% identical), LGR6 (18% identical), LGR5 (18% identical), LRIG3 (18% identical), LRIG2 (17% identical), LGR4 (15% identical), LRIT3 (15% identical), ELFN1 (14% identical), TRIL (14% identical), and 10 more.
Diseases named in the same sentence as LGI3 in open-access papers:
LGI3 is named in the same sentence as 18 diseases in open-access papers, as found by Europe PMC text mining. Sharing a sentence is not in itself a finding about the gene and the disease. The quoted sentences say what the papers report.
epilepsy (2 papers, 2011 to 2023). A brain disorder characterized by episodes of abnormally increased neuronal discharge resulting in transient episodes of sensory or motor neurological dysfunction, or psychic dysfunction. "ADGRG1, LGI3 and NEFM are known to play roles in neural development and are associated with neurological diseases, such as epilepsy." (PMID 37185447, 2023). "However, LGI3 does not rescue the LGI1 knockout mouse epilepsy, and therefore the two proteins are at least not interchangeable." (PMID 21829378, 2011).
glioma (2 papers, 2018 to 2024). A benign or malignant brain and spinal cord tumor that arises from glial cells (astrocytes, oligodendrocytes, ependymal cells). "Studies have revealed that low expression levels of LGI3 are obviously associated with poor prognosis of glioma." (PMID 30405856, 2018).
atopic dermatitis (1 paper, 2020). "This study aimed to restore the skin barrier function from atopic dermatitis (AD) via treatment with leucine-rich glioma inactivated 3 (LGI3) peptide." (PMID 32785038, 2020).
developmental delay (1 paper, 2023). "We have recently described a cohort of patients homozygous for inactivating mutations in LGI3 that display facial myokymia and developmental delay." (PMID 36828548, 2023).
Obesity (1 paper, 2016). Accumulation of substantial excess body fat. "The leucine-rich repeat LGI family, member 3, LGI3, is thought to have its function altered in obesity and to suppress adipogenesis." (PMID 26979536, 2016).
pancreatic adenocarcinoma (1 paper, 2024). "This study aimed to analyze differentially expressed genes in pancreatic adenocarcinoma (PAC) tissues and PAC cohort data in order to evaluate the prognostic role of LGI3." (PMID 38394487, 2024).
pancreatic cancer (1 paper, 2024). "Intriguingly, LGI3 is a prognostic marker of pancreatic cancer and regulates a number ofrelevant genes." (PMID 39697323, 2024).
cancer (2 papers, 2022 to 2024). A tumor composed of atypical neoplastic, often pleomorphic cells that invade other tissues. "Leucine-rich glioma inactivated 3 (LGI3) transduces signals through proteins implicated in cancer and its higher expression correlates with higher survival rates indicating its tumor suppressive nature in cancer." (PMID 36699376, 2022). "The KEGG pathway analysis of LGI3-regulated and PAC-altered genes also demonstrated that the gene groups were associated with the pathways of hypoxia-inducible factor-1 (HIF-1), TNF, cytokines, infectious diseases, and cancer-related pathways." (PMID 38394487, 2024). "LGI3 may also be involved in cytokine networks in various cancers." (PMID 38394487, 2024).
tumor (2 papers, 2022 to 2024). "LGI3 expression was correlated with the tumor-infiltration levels of various immune cells." (PMID 38394487, 2024). "This study proposes, therefore, that LGI3 plays both a pathological and a prognostic role in PAC progression by influencing cytokine network in the tumor microenvironment." (PMID 38394487, 2024). "Analysis of tumor-immune infiltrations in PAC by TIMER showed that infiltration levels of macrophages, monocytes, myeloid dendritic cells (mDC), CD4 + T cells, CD8 + T cells, natural killer cells and memory B cells were positively correlated with LGI3 expression significantly." (PMID 38394487, 2024).
LGI3 also shares sentences with these, for which no sentence is quoted: head and neck squamous cell carcinoma (2 papers); atrial fibrillation (1); brain tumors (1); colorectal cancer (1); infectious disease (1); invasive breast carcinoma (1); lung carcinoma (1); neurological diseases (1); non-small cell lung carcinoma (1).